SOX2 (SRY-box transcription factor 2)
Diseases named in the same sentence as SOX2 in open-access papers (continued):
Sharing a sentence is not in itself a finding about the gene and the disease.
nasopharyngeal carcinoma (continued). "Then, the effects of SOX2 depletion on nasopharyngeal carcinoma tumorigenesis were assessed." (PMID 30108202, 2018). "Importantly, our data demonstrate that the interaction of KLF4 and SOX2-induced expression of PI3K/AKT signaling is a critical mechanism for SOX2-driven nasopharyngeal carcinoma proliferation." (PMID 30108202, 2018). "Together, our study suggest that SOX2 exhibits oncogenic properties and may be a reliable molecular biomarker in nasopharyngeal carcinoma." (PMID 30108202, 2018). "Finally, we examined the relationship of SOX2 expression and nasopharyngeal carcinoma patient survival by Kaplan–Meier survival analysis." (PMID 30108202, 2018). "Taken together, these results clearly indicated that KLF4 could directly binds to SOX2 and might serve as a oncogenic molecular prognostic marker for nasopharyngeal carcinoma." (PMID 30108202, 2018). "In order to further determine whether SOX2 is critical for nasopharyngeal carcinoma tumorigenesis, we employed an subcutaneous nasopharyngeal carcinoma model." (PMID 30108202, 2018). "Furthermore, the SOX2-ANRIL-β-catenin axis plays important roles in nasopharyngeal carcinoma proliferation in vivo." (PMID 29463902, 2018). "However, further explorations are required to elucidate the functions of SOX2 in tumor progression, including nasopharyngeal carcinoma." (PMID 30108202, 2018). "However, the clear mechanisms under the SOX2 induced oncogenesis in nasopharyngeal carcinoma are still poorly understood." (PMID 30108202, 2018). "Furthermore, we successfully demonstrated that KLF4 serves as a oncogene and directly binds to SOX2 in nasopharyngeal carcinoma." (PMID 30108202, 2018). "Our study indicates that the SOX2-ANRIL-β-catenin pathway may provide new opportunities for the development of therapeutic agents in human nasopharyngeal carcinoma." (PMID 29463902, 2018). "Moreover, AKT was recently reported to modulate SOX2 transcriptional activity via p27 and a regulatory circuit involving miR-30a in human nasopharyngeal cancers." (PMID 26498353, 2015). "Albeit a number of these proteins have been shown to play a role in cancer, we chose to investigate the role of Sox1 in our model since it is very homologous to the induced pluripotent stem cell (iPS) regulator Sox2, and has been shown to play a role in progression of lung and nasopharyngeal cancer." (PMID 20929579, 2010). "We found SOX2 expression was markedly overexpressed in nasopharyngeal carcinoma cell lines compared with NP69 cells, suggesting that higher SOX2 expression may be associated with nasopharyngeal carcinoma phenotype." (PMID 30108202, 2018). "Finally, we examined the mechanisms by which SOX2 regulates nasopharyngeal carcinoma tumorigenesis." (PMID 30108202, 2018). "We expect that the results of the present study may shed light into a novel mechanism underlying the function of transcription factor SOX2 and KLF4 in nasopharyngeal carcinoma, and provide a rationale for its early detection and effective therapeutic strategies." (PMID 30108202, 2018). "Targeting SOX2 might be a promising treatment strategy for nasopharyngeal carcinoma treatment." (PMID 30108202, 2018). "In nasopharyngeal carcinoma (NPC), phosphorylation of SOX2 by ERK permits its subsequent SUMOylation at K245, leading to the autophagic degradation of SOX2." (PMID 38331879, 2024). "In a preclinical model of nasopharyngeal carcinoma, XIAP maintained stemness by stabilizing the SOX2 protein, extending its half-life by inhibiting autophagic degradation." (PMID 38612911, 2024). "In a preclinical model of nasopharyngeal carcinoma, DC120 significantly reduced tumor volume and CSC in both primary and secondary xenograft tumors, which they attributed to a decrease in SOX2 expression." (PMID 38612911, 2024). "Studies have shown that EphA2 pS897 activates the AKT, STAT3, SOX-2, and c-MYC signaling pathways and plays a crucial role in nasopharyngeal carcinoma stem cell formation." (PMID 37063424, 2023).
nasopharyngeal carcinoma (continued). "Our previous study revealed that SOX2 promotes VM formation in CRC cells, while more recent studies have reported that inhibition of glycolysis suppressed VM formation in nasopharyngeal carcinoma." (PMID 38044399, 2023). "Phosphorylation of EphA2 at S897 mediates the activation of the AKT, STAT3, SOX-2, and c-MYC signaling pathways, which is crucial to nasopharyngeal carcinoma stem cell formation." (PMID 37063424, 2023). "Mechanistically, SOX2 binds with ANRIL and increases its RNA level, which upregulates β-catenin signalling, resulting in enhanced nasopharyngeal carcinoma tumourigenesis." (PMID 29463902, 2018). "The western blotting assay revealed that knockdown of SOX2 markedly decreased AKT phosphorylation, which strongly suggested that SOX2 regulates nasopharyngeal carcinoma cell proliferation and tumor growth through PI3K/AKT signaling." (PMID 30108202, 2018). "Knockdown of SOX2 markedly decreased AKT phosphorylation, suggesting that SOX2 regulates AKT activity in nasopharyngeal carcinoma." (PMID 30108202, 2018). "Subsequently, lentivirus-mediated short hairpin RNAs (shRNA) of SOX2 or a control shRNA was used to deplete SOX2 in HNE-1 and C666-1 nasopharyngeal carcinoma cell lines." (PMID 30108202, 2018). "To demonstrate the role of SOX2 in nasopharyngeal carcinoma tumorigenesis, we first compared the expression of SOX2 in C666-1, SUNE-1, HNE-1, CNE1, and CNE2 nasopharyngeal carcinoma cell lines and NP69 normal nasopharyngeal cell line." (PMID 30108202, 2018). "A previous report showed that β-catenin might be a regulator of stem cell markers and could affect the expression of SOX2, c-MYC and vimentin in nasopharyngeal carcinoma cells." (PMID 33089188, 2020). "Similarly, SOX2 and KLF4 jointly drive PIK3CA expression in nasopharyngeal carcinoma, thus enhancing PI3K/AKT activity and tumorigenesis, while overexpression of PI3KCA rescues growth inhibitory effects imposed by SOX2 knock-down." (PMID 31477842, 2020). "SOX2 was markedly overexpressed in nasopharyngeal carcinoma compared with non-cancerous nasopharyngeal tissue." (PMID 30108202, 2018). "In order to explore whether similar phenomenon exists in nasopharyngeal carcinoma, a protein–protein interaction network was built according to the STRING database, which exhibited that plenty of proteins interacts with SOX2 including KLF4." (PMID 30108202, 2018). "IHC staining assays also confirmed that SOX2 was overexpressed in clinical nasopharyngeal carcinoma tissues compared to that in non-cancerous tissues." (PMID 30108202, 2018). "SOX2 is a transcription factor that contributes to transcription modification and cancer, but the mechanism by which SOX2 regulates nasopharyngeal carcinoma cell proliferation is not well understood." (PMID 30108202, 2018). "In summary, SOX2 promotes the ANRIL-β-catenin pathway, leading to nasopharyngeal carcinoma growth." (PMID 29463902, 2018). "In addition, inhibition of SOX2 by shRNA strongly inhibits ANRIL expression, indicating that SOX2 and ANRIL are required for nasopharyngeal carcinoma proliferation and tumourigenesis." (PMID 29463902, 2018). "Moreover, evaluation of nasopharyngeal carcinoma patient samples revealed a negative correlation between expression of SOX2 and survival of nasopharyngeal carcinoma patients." (PMID 30108202, 2018). "In the present study, we investigated the expression of CD133, Nanog and Sox2 in the nasopharyngeal carcinoma cell line CNE2 and primarily cultured NPC cells using immunofluorescence or flow cytometry." (PMID 23604326, 2013). "In 2010, we found that ESC protein markers CD133+, SOX2 and OCT4 were expressed in a small subpopulation of cells in human primary nasopharyngeal carcinoma (NPC)." (PMID 23443123, 2012).
head and neck cancer (31 papers, 2013 to 2025). A primary or metastatic malignant neoplasm affecting the head and neck. "The PIK3CA and SOX2 genes map at 3q26, a chromosomal region frequently amplified in head and neck cancers, which is associated with poor prognosis." (PMID 38473941, 2024). "Even in head and neck cancer, SOX2 and its associated pathway have been presented as novel biomarkers but the results are controversial." (PMID 33182283, 2020). "Increasing numbers of studies regarding the association between SOX2 and malignant tumors (e.g., head and neck cancer) have been reported." (PMID 28837080, 2017). "Some of these genes are even associated with a characteristic role in the tumorigenesis of head and neck carcinoma (like SOX2, CRYAB, and PTHLH)." (PMID 37455825, 2023). "PAI-1 promotes the proliferation of head and neck cancer tumor-initiating cells (TICs) by increasing SOX2 expression." (PMID 34113619, 2021). "By contrast, the proneural marker SOX2 was downregulated, consistent with previous publication in head and neck cancer on the inverse relationship between SOX2 and vimentin." (PMID 30967630, 2019). "Additional prospective clinical studies (such as blinded detection of CD133 and SOX2 expression) are essential to obtain more firm results in different cancer types, such as colorectal, lung, breast, and head-neck cancer." (PMID 30693028, 2019). "Lastly, knockdown of Sox2 using siRNA in head and neck cancer was found to result in a down-regulation of ABCG2, a CSCs marker known to be associated with chemo-resistance." (PMID 29401647, 2018). "Many of these events are essential for the CSC properties such as Nanog/Oct4/Sox2 expression, spheroid/clone formation, self-renewal, tumor cell migration/invasion, survival and chemotherapeutic drug resistance in HA-activated head and neck cancer." (PMID 28837080, 2017). "Overexpression of Nanog/Sox2/Oct4 has also been closely correlated with higher histological grades and poorer clinical survival in head and neck cancer." (PMID 28837080, 2017). "In head and neck cancers, the inhibition of Gsk3β also reduced the expressions of stem cells markers such as Oct4, Sox2, and Nanog, but increased the levels of differentiation markers Calgranulin B and Involucrin in CD44high/ESAhigh cells fraction." (PMID 28076327, 2017). "These may be etiologic findings since a meta-analysis of SOX2 expression in head and neck cancer found that high immunoexpression leads to worse five-year survival." (PMID 35296132, 2022). "Additionally, radiotherapy induced the dedifferentiation of head and neck cancer cells into stem cells and increased plasticity by Yamanaka reprogramming factors (transcription factors Oct4 (Pou5f1), Sox2, cMyc and Klf4) in HPV-negative cell lines." (PMID 30875950, 2019). "Furthermore, a recent study reported that SOX2, Slug and ALDH are overexpressed in human head and neck cancer 30-33." (PMID 32218701, 2020). "Furthermore, detailed head and neck cancer CSC biomarkers and their transcription factors are reviewed as CD44, CD133, ALDH, cMET and Oct-4, Nanog, Sox2, respectively." (PMID 30875950, 2019). "To investigate the relationships between EMT, CSCs and TRAF6 in head and neck cancer, we discovered that the expression of TRAF6 in SCCHN was significantly correlated with EMT markers (i.e. Vimentin and Slug) and CSC markers (i.e. CD44, KLF4, ALDH1 and SOX2)." (PMID 29193723, 2018). "So far, SOX2 expression and its clinical relevance for other head and neck cancers, such as adenoid cystic carcinoma (HNACC) have not been sufficiently investigated." (PMID 29596469, 2018).
head and neck cancer (continued). "Head and neck cancer cells belonging to the stem cell population are distinguished by the high expression of certain surface proteins (e.g., CD10, CD44, CD133), pluripotency-related transcription factors (SOX2, OCT4, NANOG), and increased activity of aldehyde dehydrogenase (ALDH)." (PMID 37453969, 2023). "Nevertheless, whether the expression of SOX2 correlates with prognosis has not yet been determined, and the results vary from organ to organ, even in the head and neck cancer subsites." (PMID 33182283, 2020).
triple-negative breast carcinoma (31 papers, 2016 to 2025). An invasive breast carcinoma which is negative for expression of estrogen receptor (ER), progesterone receptor (PR), and human epidermal growth factor receptor 2 (HER2). "SOX2 is an oncogenic transcription factor overexpressed in nearly half of the basal-like triple-negative breast cancers associated with very poor outcomes." (PMID 34502261, 2021). "This study was conducted to assess the immunoexpression of P63 and SOX2 in triple negative breast cancer (TNBC), and to evaluate the predictive diagnostic value of these markers for specific types of TNBC." (PMID 29527291, 2017). "Finally, Sox2 has been associated with tamoxifen resistance of hormone-dependent breast cancers, and paclitaxel resistance of triple-negative breast cancer cells." (PMID 33553286, 2020). "Prior studies in triple-negative breast cancer have implicated IGF2BP3 in the genesis and function of cancer stem cells, through direct regulation of SLUG transcripts, which in-turn regulates Sox2." (PMID 37760460, 2023). "RMST has been reported to be deregulated in a series of human cancers, to play an anti-oncogenic role in triple-negative breast cancer, and to modulate neurogenesis by interacting with SOX2." (PMID 37393309, 2023). "According to the literature review, we found that SOX2 is related to ceRNA network in various diseases, encompassing triple negative breast cancer and osteoarthritis." (PMID 35551606, 2022). "Mir-574-5p targets Bcl11a and Sox2 to attenuate proliferation in triple-negative breast cancer cells and governs cell proliferation through the Wnt/β-catenin pathway in PTC-1 cells." (PMID 36207684, 2022). "Noteworthy previous studies had shown that TRIB3 promotes tumor development and resistance to therapy in triple negative breast cancer models by regulating the NOTCH pathway or the stability of SOX2 via AKT inhibition and stabilization of FOXO1." (PMID 34771470, 2021). "This study explored the expression, biological function and prognostic role of SOX2 in triple negative breast cancer (TNBC)." (PMID 30186173, 2018). "In addition, increased expression of stemness markers OCT4 and SOX2 in Doxorubicin-resistant triple negative breast cancer cells has been observed, supporting the role of these genes in maintaining CSC traits across cancer types." (PMID 40251609, 2025). "This locus contains the transcription factor BCL11A, a known oncogene in triple-negative breast cancer and B-cell lymphoma, that has been described as integral to the pathology of lung squamous carcinoma through its interaction with SOX2 to control the expression of epigenetic regulators." (PMID 37871126, 2023). "We have previously identified a novel intra-tumoral dichotomy in triple-negative breast cancer (TNBC) based on the differential responsiveness to a reporter containing the Sox2 regulatory region-2 (SRR2), with reporter responsive (RR) cells being more stem-like than reporter unresponsive (RU) cells." (PMID 28427212, 2017). "Importantly, MYC is found to bind to and regulate SOX2 gene expression in CSCs derived from triple negative breast cancer, suggesting MYC can regulate cancer stemness by modulating the expression of other critical embryonic stem cell markers such as Sox2." (PMID 27821172, 2016). "Notably, the Sox2/histological grade association is significant in luminal but not triple-negative breast cancers." (PMID 33553286, 2020). "A study on triple-negative breast cancer (TNBC) also supports this mechanism: it found that THOC2, dependent on THOC5, facilitates the export of SOX2 and NANOG transcripts, thereby enhancing stemness features and radioresistance." (PMID 40901498, 2025). "Similar findings were observed in a study examining triple-negative breast cancer using a molecular reporter similar to SORE6, the SRR2 reporter, which detects the transcriptional activity of Sox2." (PMID 38203669, 2023).
triple-negative breast carcinoma (continued). "Taken together, these data suggests that SOX2 and TWIST1 are major regulators of CSC features in human triple negative breast cancers." (PMID 28835684, 2017). "Notch1 and Sox2 have been shown to act in a negative feedback loop to suppress each other in triple-negative breast cancer, and Sox2+ tumours have enhanced CSC attributes compared to Notch1+ tumours." (PMID 40754577, 2025). "Moreover, KDM5B inhibited the expression of pluripotency genes, SOX2 and NANOG, and decreased the stem cell population in triple-negative breast cancer cell lines (TNBC)." (PMID 31776402, 2019).